RNU6-661P (RNA, U6 small nuclear 661, pseudogene)
Gene: Small nuclear RNA gene on chromosome 5 (62,443,176 to 62,443,282, forward strand). Ensembl gene ENSG00000199279.
Homologues: Orthologues: chimpanzee U6 (97% identical), pig U6 (76% identical), guinea pig U6 (70% identical), rat LOC120095372 (67% identical). Paralogues in human: RNU6-97P (84% identical), RNU6-333P (83% identical), RNU6-43P (83% identical), RNU6-820P (83% identical), RNU6-971P (83% identical), RNU6-1011P (82% identical), RNU6-1083P (82% identical), RNU6-1124P (82% identical), RNU6-11P (82% identical), RNU6-1216P (82% identical), RNU6-1249P (82% identical), RNU6-28P (82% identical), and 1288 more.